CAT (catalase)
Diseases named in the same sentence as CAT in open-access papers (continued):
Sharing a sentence is not in itself a finding about the gene and the disease.
infection (continued). "Among them, the variety “Savalan” exhibited the highest resistance to the disease, with POX (at 3wpi), CAT, SOD, and PAL enzyme activities increased by fourfold, 1.5-fold, 6.8-fold, and 2.7-fold, respectively, after three weeks of infection." (PMID 41022942, 2025). "The temporary silencing of PbrGLYI-28 resulted in diminished antioxidant enzyme activities, specifically catalase (CAT), peroxidase (POD), and superoxide dismutase (SOD), during infection." (PMID 40097973, 2025). "With the continuous accumulation of H2O2 during infection, APX and CAT are required to further convert it into H2O2 and O2, thereby reducing the toxicity of H2O2 to alfalfa cells and maintaining intracellular redox balance." (PMID 40822715, 2025). "At 36 h post-infection, GSH levels surged, compensating for reduced CAT activity and working with POD to restore H2O2 levels." (PMID 40559070, 2025). "SOD activity decreased post-infection, suggesting an overwhelmed oxidative stress response, while POD and CAT were significantly upregulated, which are likely compensatory mechanisms to detoxify hydrogen peroxide and limit oxidative damage." (PMID 41009055, 2025). "The results indicate that the expression of ZmPR5 is up-regulated upon infection by Fusarium verticillioides, with significant differences observed in the activities of POD, SOD, CAT, MDA, electrical conductivity, and chlorophyll content." (PMID 40094654, 2025). "Our data are consistent with those observed in ZIKV-infected neuronal and liver cells, in which catalase and SOD-1 levels decrease during infection, facilitating viral pathogenesis." (PMID 40572291, 2025). "In the inoculated untreated plants (INO treatment), CAT activity was noticeably lower when compared to all other treatments, starting at 3 dpi, then significantly decreasing at 9 and 21 dpi, suggesting that pathogen infection might have compromised the antioxidative defence system." (PMID 41304631, 2025). "Both CAT and SOD activity were also decreased in the presence of 2% Aq, a consequence of decreased infection." (PMID 39857423, 2025). "Following B. cinerea inoculation and an additional 72-h infection period, we measured enzyme activity again, and the results showed that SlRP5 pretreatment significantly increased SOD, CAT, and POD levels, thereby enhancing plant protection." (PMID 40034157, 2025). "At 90 days post-infection with RKN, activities of SOD, CAT, and POD, as well as MDA content in leaves and roots of tobacco graft progeny, varied relative to T0." (PMID 40949564, 2025). "Post-infection, this effect became more pronounced; both SOD (p = 0.0124), CAT (p = 0.0226), and GPX (p = 0.0246) activities were significantly elevated in the supplemented groups compared to control." (PMID 41188425, 2025). "Vibrio species infection typically activates the expression of various immune-related genes in shrimp, such as ACP, SOD, CAT, PO1, and PO2." (PMID 40005752, 2025). "Following infection with fire blight, we observed a significant increase in the activities of PPO and CAT in resistant Duli, demonstrating highly significant differences when compared to susceptible strains." (PMID 40507885, 2025). "These tissue-specific increases in CAT and POX activities imply that the host plant develops a localized defense strategy in response to dodder infection." (PMID 41465831, 2025). "Antioxidant and immune enzyme activities, including SOD, CAT, and MDA in the skin, gill, and liver, and LYZ and Na+/K+-ATPase in the skin and gill were monitored from 0 to 72 hours post-infection (hpi)." (PMID 40740775, 2025). "Secondly, the antioxidant role of CAT or SOD has become unnecessary in the presence of Aq, probably due to the decreased infection rate mediated via a separate mechanism." (PMID 39857423, 2025).
infection (continued). "In research focusing on rice sheath blight, it was observed that post-infection, the expression levels of PR genes and the activities of SOD, CAT, and PAL in the leaves and leaf sheaths of two rice varieties increased." (PMID 40507885, 2025). "The ROS scavenging system in fungi (including antioxidant enzymes such as SOD, CAT, POD, GPX and GR) reduced the toxicity of ROS, maintained intracellular oxidative homeostasis, and ultimately promoting infection." (PMID 39590720, 2024). "Collectively, these outcomes signify that MvfR increased ROS production during infection, which should also be attributed to suppressed SOD and impaired catalase activity." (PMID 38860823, 2024). "Plants adapt to pathogen infection through the production of defense enzymes such as phenylalanine ammonia-lyase (PAL), peroxidase (POD), catalase (CAT), superoxide dismutase (SOD), and polyphenol oxidase (PPO)." (PMID 38760706, 2024). "Following infection, the activity of POD, CAT and GST were increased significantly in both genotype, while the SOD activity was increased significantly in DR genotype rather than DS genotype." (PMID 39700207, 2024). "Meanwhile, the increased activities of CAT and POD in the resistant line X149 were found after SC15 infection and can reduce the damage of ROS to cells." (PMID 38790195, 2024). "In this study, in comparison to the WT, the parameters of Pro, SOD, CAT, and POD were significantly increased after infection with the gray mold, while the parameter of MDA was significantly decreased after the overexpression of CYP710A11." (PMID 39062632, 2024). "The ROS scavenging system in fungi (including antioxidant enzymes such as SOD, CAT, POD, GPX, and GR) reduces the toxicity of ROS, maintains intracellular oxidative homeostasis, and ultimately promotes infection." (PMID 39452678, 2024). "Secondly, it has resulted in reduced oxidative stress as indicated by the reduced levels of catalase (CAT) (P < 0.0001) and superoxide dismutase (SOD) (P = 0.0003) produced by the TGP cells during infection and in the presence of 0.125% Aq." (PMID 38797844, 2024). "In response to this oxidative stress due to pathogen infection, an enzymatic antioxidant system with the action of SOD, APX, CAT, and GR activities takes place to keep the generation of reactive oxygen species (ROS) at physiologically accepted levels." (PMID 38498536, 2024). "Field-sprayed Azoxystrobin exhibited the lowest BLSB infection, correlating with heightened antioxidant enzyme activity (SOD, CAT, POX, β-1,3-glucanase, PPO, PAL), similar to the Validamycin-treated plants." (PMID 38666922, 2024). "Compared with Bt0h, the activities of CAT, SOD and GPx increased at 6 h, 12 h and 24 h after Bt infection, and decreased after reaching the highest value at 6h." (PMID 39519375, 2024). "Curiously, during the infection of A. aegypti females with WTR strains, there is a downregulation of inducible-catalase and an increase in H2O2 production by midgut epithelial cells." (PMID 39159809, 2024). "The increase in ROS production due to MvfR’s contribution to infection led us to investigate the effect of MvfR on the activity of two detoxifying enzymes: superoxide dismutase (SOD) and catalase (CAT)." (PMID 38860823, 2024). "During infection in A. alternata, SOD, CAT, and GPX activities were increased in response to the ROS burst." (PMID 39452678, 2024). "Cell biochemical determination showed that the MDA content and CAT, SOD and GPx activities in the larvae changed after Bt infection, indicating that the metabolism of the larvae changed after Bt infection." (PMID 39519375, 2024).
infection (continued). "The decrease in catalase and SOD2 in different brain regions after BoDV1 infection, particularly in Wt and TNFR2ko mice, very likely destabilizes intracellular redox homeostasis, leading to oxidative stress and mitochondrial damage and loss." (PMID 38339126, 2024). "Our findings indicate that CAT, SOD, GST, and, to some extent, GR activity in the ECEs’ heart tissue is influenced by HAdV-D36 infection, which leads to changes in the oxidative processes and hypertrophy of the heart tissue." (PMID 38397017, 2024). "In contrast to the previous genes, CAT and GPX showed a bimodal expression profile, indicating they were up-regulated steadily during the early stage of infection (2 and 4 dpi) in cv." (PMID 39365760, 2024). "The results showed that Bt infection damaged the midgut tissue of D. kikuchii larvae, increased the MDA content and induced the activities of CAT, SOD and GPx to increase, which played an immune defense role and reduced the body damage." (PMID 39519375, 2024). "In this study, we founded that the SOD, POD and CAT activities of WT were significantly higher than those of TRV-WRKY15-1 within 24~72 h after inoculation.We speculated that the silencing of CmWRKY15-1 delayed the response of antioxidant enzymes to the infection of pathogens." (PMID 36968373, 2023). "More importantly, we measured the activities of peroxidase (POD), catalase (CAT), phenylalaninammo-nialyase (PAL), and polyphenol oxidase (PPO) enzymes in plants after infection on the 8th day." (PMID 36834908, 2023). "Another study indicated that catalase controls oxidative damage in the midgut upon consumption of DENV infected blood meal by the Aedes mosquitoes, but it also increases infection prevalence in the mosquitoes." (PMID 37130109, 2023). "However, depletion of the peroxisomal catalase CatP does not impair H. capsulatum virulence during infection due to a redundant cell-surface-localized catalase, CatB, indicating the loss of peroxisomal CatP localization does not underlie the strong virulence attenuation of the peroxisomal mutants." (PMID 37432032, 2023). "The activity of the antioxidant enzymes (SOD, CAT, APX and PPO) and H2O2 generation were assessed to evaluate the host reaction response to infection with the AMV isolates here studied (AM1, AM2, AM3, and AM4)." (PMID 37723462, 2023). "The activities of CAT, POD, SOD, and GST in B. odoriphaga 4th-instar larvae were determined after infection with M. hiemalis spores." (PMID 36835731, 2023). "Then, caspase-3 of apoptosis protease and two antioxidant enzyme activities (CAT and SOD) increased significantly after infection, and were significantly higher in the second response than they had been in the first round." (PMID 37569567, 2023). "CAT, a representative antioxidant enzyme that detoxifies cells by removing H2O2, exhibited small changes in activity after infection." (PMID 37371894, 2023). "When Aq was used during infection, a significant reduction in H2O2 was observed concomitant with a significant increase in the levels of CAT and SOD enzymes." (PMID 37514180, 2023). "SOD, CAT, and POD enzyme activities in wild-type plants gradually increased as the infection time of the rice blast fungus changes from 0 hpi to 24 hpi and 48 hpi." (PMID 38276021, 2023). "T. hamatum strain Th23 induces CAT, SOD, and PPO enzymatic activity in tomato plants during infection with TMV and reduces H2O2 and malondialdehyde (MDA) concentrations." (PMID 36771517, 2023). "In treatments with B. subtilis, the activities of (CAT), (POX), and (PPO) were significantly increased, resulting in reduced infection." (PMID 37631164, 2023). "A study with brown trout (Salmo trutta trutta) showed that infection with A. hydrophila reduced the activity of SOD and CAT enzymes." (PMID 37958062, 2023). "SOD1, SOD2, and Catalase expression were studied, finding SOD1 downregulation after 24 and 48 h of infection." (PMID 36358519, 2022).
infection (continued). "The experiment proved that after inoculation with FOF, faba beans try to mobilize the antioxidant system and increase the gene expression of CAT and SOD to resist the infection of FOF." (PMID 36325572, 2022). "Detoxification enzymes, such as catalase and SOD, are produced during all infection courses by microorganisms in order to face the reactive oxygen species produced by host phagocytic cells." (PMID 36354939, 2022). "Six oxidative-redox proteins including ferredoxin, catalase isozyme and peroxidase were both up-regulated after FOC infection at 2dpi and 4dpi." (PMID 35698057, 2022). "The expression levels of genes such as SOD, PPO, CAT, POD and glutathione peroxidase (GPX) were mainly upregulated, especially for PPO and POD, which showed high expression during infection." (PMID 36008749, 2022). "Therefore, an acute decrease in SOD, CAT, and GPx at the beginning of S. agalactiae infection in this study may be related to the rapid energy depletion of the organism at the beginning of the infection." (PMID 36139883, 2022). "At the same time, POD activity was observed earlier than the peak activity of CAT and SOD, indicating that H2O2 plays an important role in disease resistance during the early infection stage in oil tea." (PMID 36438122, 2022). "Additionally, the expression of catalase (TRINITY_DN19585_c0_g1) was significantly up-regulated in the middle stage of infection (36 hpi), and the expression of glutathione S-transferase (TRINITY_DN14304_c0_g1) was increased in the late stage of infection (48 hpi)." (PMID 36304957, 2022). "During infection with the influenza virus, EGCG and quercetin increased the level of antioxidant enzymes such as catalase (CAT), glutathione (GSH), and superoxide dismutase (SOD) and thereby suppressed oxidative stress." (PMID 34764869, 2021). "Because catalase and SOD were detected in the capsular extract and reacted with sera of the cCE-immunized pigs, we presume that these antibodies had neutralizing effects on catalase and SOD of G. parasuis in PAMs infection." (PMID 33968026, 2021). "In apricots, PPV infection produced a drop in class I APX, CAT, POX, and DHAR, as well as an increase in PPO." (PMID 34357359, 2021). "Pathogen infection inevitably leads to changes in photosynthesis parameters, including Pn, Gs, and Ci; biochemical materials such as SOD and CAT; signaling molecules such as H2O2 and hormones; and the expression of genes involved in photosynthesis." (PMID 34445571, 2021). "The Snn3–SnTox3 interaction inhibited H2O2 production in wheat at the early stage of infection by affecting four enzymes of redox metabolism: NADPH-oxidases, peroxidases, superoxide dismutase and catalase." (PMID 34451631, 2021). "During the infection period, the activities of SOD, POD, and CAT were generally higher in KPF-treated leaves than in those from the control group, especially for the 3% KPF treatment." (PMID 35082814, 2021). "The activities of CAT and POD were observed to be much higher in transgenic tobacco and GL-3 plants than in their respective WT and empty vector lines after infection with pathogens." (PMID 34629466, 2021). "Our results show that cytokinins and SA trigger defense reactions in wheat against S. nodorum due to the induction of oxidative burst at an early stage of infection by acting on the enzymes of redox metabolism, such as NADPH oxidase, peroxidase, and catalase." (PMID 33525389, 2021). "nodorum pathosystem, the antagonism of ethylene on the one hand and CK and SA on the other hand at the early stages of infection manifested itself in the effect on redox enzymes—NADPH oxidase, peroxidase, and catalase." (PMID 33525389, 2021). "In this study, after the injection of NAC oxidative stress levels were significantly reduced in the pathogen infection group and the mRNA levels of SOD, CAT, GSTCD, and GSTO1 increased significantly." (PMID 33574492, 2021).
infection (continued). "Enzymes with catalase (CAT), peroxidase (PO), and polyphenol oxidase (PPO) activity were increased during the first hours of infection in plants that had been treated with chitosan." (PMID 34207947, 2021). "The results indicated that the activities of SOD, CAT and T-AOC were significantly decreased after infection with A. hydrophila (P < 0.05), and the supplementation of AKG generated a remarkable increase of the activities of CAT and T-AOC (P < 0.05)." (PMID 34220849, 2021). "After infection with DIV1 at 24 hpi, the activities of SOD, CAT, LYZ, and PO in the plasma were detected to evaluate the effect of DIV1 infection on the immune enzymes of M. japonicus." (PMID 34512588, 2021). "The antioxidant enzyme activities of T-SOD, CAT, GPx, GST, GR and the content of GSH were significantly decreased in muscle tissues after infection with P. vulgaris and E. meningoseptica (p < 0.05)." (PMID 33574492, 2021). "Before infection, hepatic SOD and CAT activities in fish in 2 and 4‰ treatments were significantly higher than those in fish in control, 0.5 and 1‰ treatments (P < 0.05)." (PMID 34305652, 2021). "The results showed that infection of V. dahliae increased the accumulation of SOD, POD, and CAT in all overexpressing lines and after V. dahliae treatment, overexpression of miRm0002 significantly increased SOD, POD, and CAT compared to both controls." (PMID 34834637, 2021). "In a cell culture model, during the first hours after infection, SOD1, SOD2, glutathione S-transferase (GST), CAT, and GPx are induced." (PMID 33381273, 2020). "While oxidative markers such as lipid peroxidation products were increased by infection, levels of AOE were significantly reduced compared to control uninfected cells, with catalase and SOD1 being dramatically reduced at peak of viral replication (48 h)." (PMID 32107411, 2020). "Reduced H2O2 content is likely due to direct activation of CAT after the priming treatment, and higher CAT and GPX activities after infection with B. cinerea." (PMID 33255543, 2020). "The activity levels of SOD, POD, CAT, and PAL increased in response to the pathogen infection until 4 dpi and decreased thereafter." (PMID 33302873, 2020). "The activities of enzymes involved in H2O2 detoxification (CAT and APX) correlated with the level of H2O2, both after fructan treatment and in response to infection, preventing ROS from reaching excessive and damaging levels." (PMID 32882794, 2020). "RSV infection also led to inhibition in mRNA levels of catalase (CAT) and glutathione S-transferase A2 (GSTA2) at later stages of infection which coincide with ROS induction." (PMID 32461278, 2020). "IV infection can decrease the production of antioxidation targets, such as HO-1 and NQO1, SOD1, GR, CAT, and GPx1 are downstream molecules of the Nrf2 pathway after IV infection." (PMID 32689931, 2020). "After the inoculation of C. gloeosporioides, the antioxidant enzymes (POD, CAT, and APX) decreased with the prolongation of infection time in both CaChiIII2-silenced (pTRV2:CaChiIII2) and control (pTRV2:00) plants." (PMID 33374725, 2020). "qRT-PCR showed that infection with S. populiperda downregulated APX and CAT expression in transgenic and WT poplar at most time points, and APX and CAT expression was lower in transgenic than in WT poplar." (PMID 32117134, 2020). "Treatment with catalase (CAG; Sigma), which degrades H2O2 surrounding the infection site, suppressed the infection defect of the ΔMoaa91 mutants." (PMID 32209696, 2020). "We also found a primed response after infection with B. cinerea for H2O2 accumulation and the activities of ascorbate peroxidase and catalase." (PMID 32882794, 2020). "On the contrary, a single infection with RSV resulted in diminished Nrf2 and partially diminished CAT and SOD1, while expressions of NF-κB and its phosphorylated form were greatly enhanced compared to control." (PMID 32466130, 2020).